MTOR (mechanistic target of rapamycin kinase)
Diseases named in the same sentence as MTOR in open-access papers (continued):
Sharing a sentence is not in itself a finding about the gene and the disease.
tumor (continued). "To summerize, we conclude that AST is able to attenuate tumor growth by downregulation of VEGF production, which involves modulation of mTOR and COX-2 signaling." (PMID 22992293, 2012). "Combined administration of PI3K/mTOR inhibitor BEZ235 and MEK inhibitor AZD6244 to MMTV-neu mice achieved nearly complete tumor regression." (PMID 23227361, 2012). "The mTOR pathway, being a part of the PI3K/Akt is considered as a key determinant in tumor angiogenesis through the expression of hypoxia related genes VEGF." (PMID 23185335, 2012). "Moreover, there is a considerable variation in the therapeutic benefits detected in patients harbouring tumours predicted to be responders to mTOR inhibition, because the genetic context in which the altered phenotype occurs may also be important for the patient response to therapy." (PMID 22408430, 2012). "Taken together, our results demonstrate that miR-122 functions as a tumor suppressor and plays an important role in inhibiting the tumorigenesis through targeting IGF1R and regulating PI3K/Akt/mTOR/p70S6K pathway." (PMID 23056576, 2012). "Moreover, inhibition of mTOR activity by rapamycin inhibited T-bet expression and promoted memory precursor cells with improved tumor efficacy that may be attributed to alterations of cell phenotype, localization, survival and effector function upon antigen re-exposure." (PMID 22680924, 2012). "In this study 15% of HCC displayed overexpression of phospho-mTOR, whereas 45% of HCC had increased expression of p70 S6K, which correlated with tumor nuclear grade." (PMID 22470194, 2012). "Thus, a better understanding of mTOR signaling and the mechanisms of rapamycin resistance will lead to more optimal targeting of this pathway for enhancing the therapeutic efficacy in preventing and treating tumor recurrence after liver transplantation for HCC." (PMID 22428038, 2012). "Recently, miR-19a was identified as a key molecule responsible for the oncogenic activity of the cluster, and was shown to reduce the tumor suppressor PTEN level, and consequently activate the AKT/mTOR (mammalian target of rapamycin) pathway." (PMID 22952885, 2012). "mTOR also has a central role in the homeostatic proliferation of CD8 T cell memory and anti-tumor immunity." (PMID 22680924, 2012). "It is possible that in irradiated tumours conditions develop, long after delivery of IR, that attenuate signal transduction between ATM and Akt leading to suppression of Akt and mTOR activity despite enhanced ATM activation." (PMID 22607554, 2012). "Treatment with quercetin showed a sharp decrease in the phosphorylation of mTOR and p70S6K, and its upstream kinase, AKT, suggesting that quercetin suppresses tumor angiogenesis by inhibiting VEGFR2 and blocking its multiple downstream signaling components." (PMID 23094058, 2012). "Adenosine monophosphate-activated protein kinase subsequently activates another tumor suppressor, TSC1/TSC2, thereby leading to mTOR inactivation." (PMID 21837674, 2012). "Previous data showed that inhibition of mTOR by rapamycin up-regulated PDGFR expression in Tsc1−/− and Tsc2−/− cells, and subsequently enhanced PI3K/AKT activation, which reversed the impaired tumor formation by Tsc1−/− and Tsc2−/− cell lines." (PMID 22428038, 2012). "Deregulation of those proteins in many tumours has resulted in activation of PI3K and mTOR pathways and in turn to S6K activation." (PMID 22570651, 2012). "Utilizing these small molecule inhibitors, we found that the antitumor effectiveness of combined mTOR and MEK inhibition is dependent upon tumor genotype." (PMID 22808163, 2012).
tumor (continued). "We demonstrated here that targeted inhibition of mTOR significantly enhanced the generation and maintenance of CD133+ subpopulations and promoted secondary tumor re-propagation of H-Ras-transformed mouse liver tumor cells in vivo." (PMID 22145042, 2011). "Tumours that showed a response to G28UCM had a marked decrease in phosphorylated HER2, ERK1/2 and mTOR proteins and, to a lesser extent in phosphorylated AKT, without detectable changes in the total levels of the corresponding proteins." (PMID 22177475, 2011). "Sections of tumor before IGF1R antibody therapy and after IGF1R antibody combined with mTOR inhibitor therapy were available for analysis." (PMID 21494688, 2011). "By multiplex Luminex analysis, we demonstrated that a specific growth factor, VEGF, is secreted from the IH tumor spheres and that an mTOR/VEGF inhibitor, Rapamycin, dramatically inhibits IH tumor stem cell growth." (PMID 22192404, 2011). "This compound was seen to exhibit dual p110α/mTOR inhibition (IC50 = 4 and 21nM, respectively), and displayed potent in vivo tumour growth inhibition in the PC3 prostate tumour xenograft model." (PMID 21649578, 2011). "Between a third and two-thirds of patients with mRCC have tumours refractory to anti-VEGF and mTOR inhibitor treatment from the outset, and all patients inevitably acquire resistance to therapy." (PMID 22738081, 2011). "Again, data from our lab demonstrated that the blockade of mTOR with CCI-779 resulted in regional apoptosis and conversion in the character of surviving tumor cells from astrocytoma to oligodendroglioma in a mouse model of Akt+KRas-induced GBMs." (PMID 21267448, 2011). "The cytokines secreted by the few vGPCR-expressing tumor cells activate in neighboring cells multiple pathways (including AKT, ERK, p38 and IKKβ) that, in turn, converge on TSC1/2, promoting mTOR activation, HIF upregulation, and VEGF secretion." (PMID 21559457, 2011). "Immunohistochemical probes were applied to detect p-mTOR (Ser2448), p-Akt (Ser473), p-ERK1/2 (Thr202/Tyr204), nestin, and p-STAT3 (Tyr 705) in the original and recurrent tumor." (PMID 21494688, 2011). "Despite the literature demonstrating the importance of PI3K and mTOR in RCC pathogenesis, there is limited information on total protein expression and co-expression in large cohort RCC tumor studies in the context of patient survival." (PMID 21834980, 2011). "In a xenograft study, the 4EBP1 activity of tumor cells and peripheral blood mononuclear cells (PBMC) is also reduced by mTOR inhibition." (PMID 21513566, 2011). "One of the most important inducers of EMT and tumour metastasis is hypoxia and there is growing evidence of a complex interplay between the AKT/PI3K/mTOR pathway and hypoxia." (PMID 21283818, 2011). "In patient 2, upregulation of mTOR was seen in the primary tumor, perhaps explaining the initial response to the IGF1R and mTOR inhibitor combination, while the resistant tumor that emerged showed activation of the ERK pathway as well." (PMID 21494688, 2011). "Previous work carried out in transgenic EGFR and ERBB2-mutant mice showed substantial tumor regression when mice were treated with a combination of BIBW-2992 and rapamycin targeting mTOR (or more specifically TORC1)." (PMID 20111714, 2010). "We also found that mTOR signaling contributes to tumor cell survival, as demonstrated by pharmacologic inhibition of PI3K/AKT/mTOR, or total silencing of the mTOR gene." (PMID 21067588, 2010). "Sensitive tumours were characterised by gene copy number variations and overexpression of genes leading to activation of the PI3K/Akt/mTOR pathway." (PMID 20664591, 2010). "Despite the blockade of PI3K, EGFR and mTOR with efficient AKT inhibition, little apoptosis of the tumour cells was detected, again emphasizing the need to induce cytotoxic rather than cytostatic therapeutic responses." (PMID 20515495, 2010).
tumor (continued). "However, these symptoms may also be associated with infection or the tumor itself, both of which should be ruled out before attributing causality to the mTOR inhibitor." (PMID 21092307, 2010). "These selective agents acts by blocking the glucose uptake from tumor cells and they have been shown to sensitize cells to death and avoid the normal activation of the PI3K/Akt/mTOR intracellular pathway." (PMID 20706540, 2010). "We demonstrated that dual targeting of the PI3K and mTOR pathways by the novel inhibitor NVP-BEZ235, exhibited toxicity on WM cells by directly targeting the tumor clone and indirectly through an effect on the bone marrow milieu." (PMID 21317453, 2010). "Majority of this research has revealed that mTOR inhibition increases sensitivity to cell death pathways; however, there is also emerging evidence that mTOR activation may play a role in promoting cell survival through the activation of antiapoptotic proteins that contribute to tumor progression." (PMID 21584218, 2010). "In all, 28% of all patients showed coexpression of both pathways in terms of EGFR, p-mTOR and p-p70s6K positivity in SCLC tumour specimens." (PMID 20683448, 2010). "Tumor samples treated with MTA showed a diminished activity of the PI3K and mTOR pathways according to the p-Erk1/2, p-Akt and p-S6 levels." (PMID 20529342, 2010). "VN/124-1 tumours demonstrated increase in growth factor signalling with an increase in expression of IGFR1 (6.9-fold), p-HER2 (1.9-fold), p-MAPK (3-fold), p-mTOR (1.6-fold), p-P70S6K (2.6-fold), and p-PS6 (1.2-fold)." (PMID 20842117, 2010). "Another receptor tyrosine kinase inhibitor drug, sunitinib is also a strong apoptosis inducer in different tumor cells, especially in the presence of inhibitors of the PI3K/Akt/mTOR pathway." (PMID 21078198, 2010). "Additionally, because mTOR is pivotal in the cellular processes that tumor cells depend on for cellular metabolism, proliferation, survival and progression, combining an mTOR inhibitor with other anticancer agents could serve to sensitize tumor cells to these agents." (PMID 19860903, 2009). "In normal SVZ cells Akt, mTOR and its downstream targets were only transiently modulated by BMP2, indicating a different sensitivity between tumor and normal cells in responsiveness to exogenous BMP2." (PMID 19587783, 2009). "The present study was designed to interfere with the tumor cell signaling network horizontally and vertically by targeting the VEGF receptor and EGF receptor as well as the mTOR-Akt axis." (PMID 19473483, 2009). "Using a tissue microarray of clinical samples (N=86), tumour cell immunohistochemical staining of AKT/mTOR downstream targets, pS6 and p4E-BP1, together with tumour cell staining of VEGF-A and pVEGFR2 were semi-quantified." (PMID 19240722, 2009). "Consistent with suppression of the mTOR pathway, decreased 4E-BP1, p70 S6-kinase, and S6 protein phosphorylation correlated with a decrease in Wnt-1 tumor cell proliferation." (PMID 18570671, 2008). "In summary, we have demonstrated that the combination of EGCG+tamoxifen significantly reduced ER-negative tumour growth and that this was driven primarily by an enhanced effect by the decreased protein expression of the EGFR, mTOR, and CYP1B1." (PMID 18797454, 2008). "Mutations in PTEN, PML, TSC, and VHL have been identified in tumor cells that result in the deregulation of HIF via multiple distinct mechanisms involving Akt/PI3K, mTOR and the ubiquitin pathway." (PMID 18773095, 2008). "Description: A small molecule inhibitor of mTOR (mammalian target of rapamycin), part of the PI3 kinase/AKT pathway involved in tumor cell proliferation and angiogenesis." (PMID 27994701, 2008).
tumor (continued). "Lastly, five tumour specimens overexpressed both PLD1 and phospho-Akt, and two of these five tumours overexpressed phospho-mTOR." (PMID 17726467, 2007). "This was particularly true in tumours having shown the highest response under treatment (with the triple combination), AKT is one of the main mTOR-related messengers and the current development of mTOR inhibitors as anticancer drugs is very promising." (PMID 17592499, 2007). "Oestrogen receptor expression was determined from the pathology reports that accompanied each tumour specimen, and the expression of PLD1, phospho-Akt, phospho-mTOR, and CKs 5/17 was evaluated by IHC analysis." (PMID 17726467, 2007). "An additional major difference between tumours and cell lines involved phospho-RPS6, an indicator of mTOR activity." (PMID 15956968, 2005). "Compound classes such as MEK, PI3K, and mTOR, HSP, HDAC, and BET inhibitors cluster individually based on their correlations with GBM tumor single-cell expression data (Pearson’s ρ > 0.7), suggesting that biologically relevant information is retained in this perspective." (PMID 41501023, 2026). "In vitro experiments further demonstrated that SERPINE1 knockout can promote apoptosis and inhibit the mTOR pathway, suggesting that SERPINE1 may influence tumor cell behavior through these mechanisms." (PMID 41601623, 2026). "SFXN1 appears to be functionally linked with cell survival and growth promotion genes (AKT1, BCL2, MTOR) and pro-apoptotic components (BAX, CASP3), indicating its dual role in maintaining mitochondrial homeostasis and regulating cell fate decisions in tumor cells." (PMID 41399448, 2026). "In this study, the aim was to develop NPs that reduce the activity of mTOR and AURORA pathways, potentially decreasing MYCN protein enhancement and stability, by combining inhibitors and targeting them specifically to the tumor, and to demonstrate their effect in NB." (PMID 41926246, 2026). "Furthermore, dysregulation of E2F transcription factors, specifically E2F1 further contributes to tumour progression, activates the PI3K/AKT/mTOR pathway and inhibits apoptosis [71,]." (PMID 41476776, 2026). "Furthermore, our results indicate that PF-309 inhibits key signaling pathways involved in CRC progression, including the mTOR, p70 S6K, EIF4G1, NF-κB, IKB-α, c-Myc, WNT3A, and β-catenin pathways, underscoring its broad spectrum of anti-tumor effects." (PMID 41459112, 2026). "In comparison to the DMSO + PBS group, the SC79 + PBS group showed no significant change in the phosphorylation levels of PI3K in tumor cells; however, there was a significant increase in the phosphorylation levels of AKT and mTOR proteins, as well as the expression of PD-L1 protein." (PMID 40328748, 2025). "Remarkably, PD-1 expression in HCC cell extends beyond its classical role, directly activating mTOR signaling via eIF4E and S6 phosphorylation to support tumor growth independent of adaptive immunity." (PMID 40764998, 2025). "In HER2-positive tumours, CAFs are activated via HER2-driven pathways, such as PI3K/AKT and mTOR." (PMID 41463236, 2025). "By examining the foundational roles of Notch, Hedgehog, and PI3K/AKT/mTOR signaling, we gain deeper insights into the molecular underpinnings of CSC-driven tumor progression and identify promising avenues for innovative therapeutic interventions that specifically target these key nodes of stemness." (PMID 40759634, 2025). "Translating these findings to CAF biology suggests that integrin–mTOR inhibitors may synergize with PHLDA1‐targeted approaches to normalize the stroma and enhance anti‐tumor immunity." (PMID 40688078, 2025). "miR-100-3p represses tumor growth by targeting BMPR2, whereas miR-100-5p inhibits cell growth by targeting CXCR7, represses invasion and metastasis by targeting ZBTB7A, and activates the autophagic pathway by targeting mTOR." (PMID 40161350, 2025).
tumor (continued). "To investigate anti-tumor mechanisms of the compound and to elucidate connections between PI3K/mTOR signaling and distinct cell death pathways, we undertook a comprehensive analysis of YYN-37′s effects in HCT-116 and SJSA-1 cells, and performed a preliminary exploration of its underlying mechanisms." (PMID 41471338, 2025). "Intriguingly, the sensitivity of the tumor spheroids to GDC-0980, a PI3K//mTOR kinase inhibitor, was not linked to the Akt/mTOR pathway but was instead associated with the presence of ATG 13 puncta, a marker of early autophagy." (PMID 40149313, 2025). "Furthermore, western blotting revealed that p-mTOR, p-AKT, and p-PI3K levels in tumor tissues were all reduced or increased following circ_0092278 silencing or overexpression." (PMID 40537911, 2025). "In lung cancer, anisamide-functionalized oligopeptide end-modified poly (beta aminoester) (OM-pBAE) nanoparticles selectively deliver mTOR siRNA to NSCLC, maintaining stability in serum, achieving efficient transfection, and suppressing tumor growth in vitro and in vivo with tumor selectivity." (PMID 41304838, 2025). "In vitro experiments demonstrated that targeted inhibition of TREM1 not only exerted anti-tumor effects but also suppressed the PMT process in GBM and inhibited the activation of the TLR4/PI3K/AKT/mTOR signaling axis, further highlighting its clinical significance in GBM progression." (PMID 41394801, 2025). "Compared with IL-12–treated tumors, combination-treated tumors had significantly lower levels of several proteins in the PI3K/AKT/mTOR and MAPK signaling pathways (all P < 0.05), which could be due to the influence of tumor cells in the vicinity." (PMID 39777457, 2025). "Furthermore, cotreatment of UPS xenografts in immunodeficient mice with a dual PI3K/mTOR inhibitor and an anti-IGF1R kinase inhibitor reduced tumor growth in vivo, while also decreasing UPS cell migration and invasion in vitro." (PMID 41300979, 2025). "KDs may also modulate pathways such as PI3K/Akt/mTOR and activate AMPK signaling, thereby inhibiting tumor growth." (PMID 40944231, 2025). "Notably, SMAPs promoted 4E-BP1–dependent apoptosis in tumor cells and potentiated 4E-BP1 function in the presence of ERK or mTOR inhibitors, agents that rely on inhibition of eIF4E-dependent translation for antitumor activity." (PMID 39869680, 2025). "Furthermore, GSEA analysis showed reductions in genes related to anti-tumor immune responses including the IL-2/STAT5, the interferon-gamma and the PI3K/AKT/mTOR signaling." (PMID 39885132, 2025). "Upregulation of PI3K/AKT/mTOR axis can increase the levels of MRP‐related proteins including P‐glycoprotein, leading to chemoresistance and reduction in accumulation of anticancer compounds in the tumor cells." (PMID 40740483, 2025). "In addition, HIF-1/2α interacts closely with mTOR, MYC, PI3K/AKT, and other signalling pathways, jointly regulating multiple levels of tumor metabolism, including glycolysis, fatty acid synthesis, and amino acid metabolism." (PMID 41555916, 2025). "As a receptor present on the surface of tumor cells, csGRP78 can interact with various signaling molecules, leading to the initiation of downstream cascades involving STAT3, RAS/MAPK and PI3K/AKT/mTOR." (PMID 39629920, 2025). "GP73-deficient T-cells were found to detrimentally affect CD8+T cell cytotoxicity and glycolysis primarily due to its interaction with Hypoxia-inducible factor 1α and mTOR levels in hypoxic cells, suggesting a key role for GP73 in T-cell cytotoxicity within the hypoxic tumor microenvironment." (PMID 40360438, 2025). "Furthermore, HBV infection can activate several oncogenic pathways, such as the PI3K/AKT/mTOR and MAPK signaling cascades, which are also involved in angiogenesis and tumor proliferation." (PMID 40647409, 2025).